TERT (telomerase reverse transcriptase)
Diseases named in the same sentence as TERT in open-access papers (continued):
Sharing a sentence is not in itself a finding about the gene and the disease.
cancer (continued). "TERT expression is accurately regulated in various cells in order to avoid cancer cell transformation, whereas TERC is constitutively expressed in mammalian cells." (PMID 37189709, 2023). "For example, burden tests within specific cancer types have identified NCVs in the promoters of TERT, FOXA1, HES1, SDHD, and PLEKHS120–22." (PMID 36808133, 2023). "Several recent studies have analyzed TERT alterations and/or telomeres/shelterin in TCGA pan‐cancers, gaining broader insights into telomerase regulation and the role in carcinogenesis." (PMID 36239411, 2023). "The precision of TERT‐based anti‐cancer therapies will be crucial to overcome off‐target side‐effects, especially given the extra‐telomeric functions of telomerase." (PMID 37041671, 2023). "In most cancer types, TERT expression was positively correlated with its locus methylation, which was consistent with previous reports." (PMID 36239411, 2023). "Several strategies to inhibit TERT have been tested across multiple cancer types, comprising small molecule inhibitors and TERT-based immunotherapy, in particular, vaccines." (PMID 38201248, 2023). "Since TERT increases the number of cell divisions, it is believed to promote the unlimited growth of cancer cells." (PMID 37525387, 2023). "Oligonucleotides, antisense-oligodeoxynucleotides and siRNAs, that interfere with TERT mRNA and TERC itself, were shown to rapidly inhibit cancer cell growth and increase susceptibility to treatment." (PMID 37189709, 2023). "TERT is usually silenced in normal somatic cells; however, its expression lever is significantly upregulated in more than 90% of human cancer cells." (PMID 36910209, 2023). "Human telomerase reverse transcriptase (h‐TERT) is expressed in multiple types of cancer, including non‐small‐cell lung cancer (NSCLC)." (PMID 37829505, 2023). "Then, we have used an optimized reverse immunology approach to identify four novel MHC class II-restricted peptides derived from human TERT referred as “Universal Cancer Peptides” (UCP)." (PMID 37516867, 2023). "Multiple mechanisms, including telomere structure, epigenetic modification, transcriptional regulation, and apoptosis, have been suggested to explain the associations of the TERT-CLPTM1L locus and cancer susceptibility." (PMID 36769103, 2023). "The fact that TERT alterations are shared by several different malignancies reflects the importance of this gene for cancer." (PMID 38201248, 2023). "In humans, most cancer cells express high levels of TERT, whereas normal cells suppress TERT expression." (PMID 37525387, 2023). "Given the key role of TERT in telomerase activation for malignant transformation, great efforts have been made to define various impacts of TERT on cancer development and progression." (PMID 36239411, 2023). "TERT, which is essential for the chromosome telomere replication in most eukaryotes and is particularly active in progenitor and cancer cells, was also more expressed in MtrBTN2 cells." (PMID 37816387, 2023). "Taking these data into consideration, this research aim was to investigate the possible association between four TERT high-frequency SNPs rs2735940, rs2736098, rs2736100, and rs10069690 with increased risk of NSCLC in cancer subjects in Iraq." (PMID 38084250, 2023). "Sequencing of the TERT promoter in cancer cell lines showed 53% (41/77) to contain at least one heterozygous sequence variant allowing allele distinction." (PMID 37993930, 2023). "In a study by Zhang Y. and others, TERT promoter SNVs were most commonly found among HCC patients with early stage cancer in 22.3% of cases." (PMID 37298294, 2023). "In contrast, TERT is reactivated in 90% of human tumors to maintain a minimum functional telomere length to allow cancer cell division." (PMID 37085672, 2023). "Risk of cancer-specific death in DTC by AAD, which is a well-established risk factor, is partially explicable by TERT promoter mutation by 36%." (PMID 37948420, 2023).
cancer (continued). "Lastly, our team identified the crucial role of the TERT gene in the development of cancer hallmarks." (PMID 37884663, 2023). "In particular, a study has shown that telomerase repression, either through inactivation of TERT or through shRNA inhibition of telomerase, increases cell cycle arrest and apoptosis in both in vitro and in vivo cancer models." (PMID 36579897, 2023). "It is postulated that mitochondrial located TERT protects against ROS‐induced damage to the nucleus in cancer cells, thereby enhancing apoptosis resistance." (PMID 37041671, 2023). "In cluster 2, which showed high activity in the telomerase pathway related to TERT, a higher cancer signaling pathway was confirmed compared with the other clusters." (PMID 37864645, 2023). "Integration events occurring in single samples were observed in the following cancer-driver genes: TERT, KMT2B (MLL4), RIMS1, FN1, RBFOX1, CNTNAP2 and THRB7,11,12,14,27,28." (PMID 37400627, 2023). "It is well known that cancer cells become immortalized through telomere maintenance mechanisms, such as TERT activation, following cancer-specific genetic alterations such as copy number gain and recurrent promoter mutations." (PMID 37511212, 2023). "TERT is located on chromosome 5p15.33 in humans and is an integral and essential part of the telomerase holoenzyme, which plays a key role in cancer formation." (PMID 36979671, 2023). "In two types of human cancer cells, β-catenin enables cancer development by occupying the promoter of TERT and thus upregulating TERT expression." (PMID 37862118, 2023). "Telomerase reverse transcriptase (TERT) maintains telomere length by adding nucleotides to the ends of telomeres and plays a role in cellular senescence and cancer development." (PMID 37777755, 2023). "TV was significantly lower in cancer-developing cases, and the numbers of TERT-positive and NS-positive cells were significantly increased in these cases compared with non-cancer-developing cases." (PMID 36834592, 2023). "In up to 90% of human cancer cells, telomerase is reactivated through expression of its catalytic subunit TERT." (PMID 36910209, 2023). "The object of our study was the search for G4 motifs located in the promoter regions of the telomerase reverse transcriptase (TERT) oncogene, the product of which is responsible for the immortalization of cancer cells." (PMID 37511853, 2023). "An opposite effect has been observed in different cancer cell lines where resveratrol reduces TERT and induces cellular apoptosis." (PMID 36237161, 2023). "The TERT-CLPTM1L region has been extensively studied for single nucleotide polymorphisms (SNPs) and their association with various cancers, including bladder, breast, lung, prostate, and pancreatic cancer." (PMID 38254939, 2023). "Such mutations create a new binding site for the E-twenty six (ETS) family of transcription factors, resulting in the increased TERT expression which was initially observed in melanomas and later in other cancer types." (PMID 36980987, 2023). "In stem cells and most cancers, telomeres are elongated by the ribonucleoprotein complex telomerase, composed of the telomerase reverse transcriptase (TERT) catalytic component and the RNA templating component (Terc)." (PMID 37560909, 2023). "Upregulation of TERT expression and increased telomerase activity in cancer and somatic cells relate to improved survival and persistence of such cells." (PMID 37189709, 2023). "Although a therapeutic window for telomerase/TERT inhibition exists between cancer cells and somatic cells, stem cells express TERT and rely on telomerase activity for physiological replacement of cells." (PMID 37531400, 2023).
cancer (continued). "The extent to which genetic alterations of TERT play a role in cancer progression and the molecular mechanisms affected by reactivation of TERT transcription vary widely among cancer entities, making it crucial to understand the underlying mechanisms." (PMID 37418389, 2023). "For example, TERT serves as a transcriptional cofactor to regulate expression of a panel of oncogenic factors, and promotes cancer aggressiveness, resistance to oxidative stress, and anticancer drugs, and survival or proliferation." (PMID 36239411, 2023). "Considering the Afirma Gene Expression Classifier and ThyroSeq genomic classifier are not yet available in China and are expensive, 5 of the most common cancer-associated somatic mutations (BRAF, HRAS, NRAS, KRAS and TERT) were offered in our hospital." (PMID 36737779, 2023). "The vast majority of cancers overcome replicative senescence by upregulating TERT expression and telomerase activity." (PMID 36979671, 2023). "The TERT gene is one of these intriguing factors that has been shown to have a remarkable connection with the initiation and development of many cancers." (PMID 38084250, 2023). "It has been confirmed that telomerase activation is an early event in the development of cancers, especially the TERT, which plays an important role in this process." (PMID 36938425, 2023). "We used these data as the foundation for an antibody expression screen of the same proteins in our cell density experiments with the iPSCs as a means to identify SFs that regulate TERT differently or similarly between stem and cancer cells." (PMID 37531400, 2023). "In cancer types with significant TERT upregulation, levels of other telomerase components in general increased, too." (PMID 36239411, 2023). "This modification blocked the binding of transcription factors to the TERT promoter, reduced TERT transcription and TERT protein expression, and induced cancer-cell senescence and proliferative arrest." (PMID 36980699, 2023). "This activation led to an upsurge in TERT (telomerase reverse transcriptase) transcription, increased telomerase activity, and promoted cancer survival and clonal expansion." (PMID 38001739, 2023). "Further studies should aim to validate these findings in clinical settings and explore the clinical utility of DMI, providing new insights into the intricate relationship between TERT expression and cancer metabolism." (PMID 38090478, 2023). "The increased susceptibility to this anticancer drug was mediated by TERT (Telomerase Reverse Transcriptase), a downstream gene of Bmal1, whose activity was found to be under circadian control and widely activated in cancer." (PMID 37504857, 2023). "TERT promoter mutations are related to cancer aggressiveness and act as an independent poor prognostic factor in DTC, and the prevalence of TERT promoter mutation is higher in older AAD." (PMID 37948420, 2023). "The combination of these analyses revealed stem cell- and cancer cell-specific TERT regulatory factors." (PMID 37531400, 2023). "By doing so, we observed that TERT levels in tumors increased most robustly and widely, which occurred in 20/21 of cancer types except THCA." (PMID 36239411, 2023). "Next, we wanted to build upon the idea that there is a regulated TERT splicing code in stem cells and a dysregulated TERT splicing code in cancer cells." (PMID 37531400, 2023). "UCPVax is a therapeutic cancer vaccine composed of two separate peptides derived from telomerase (human TERT)." (PMID 37516867, 2023). "When targeting a somatic cancer mutation in the TERT promoter, the approach presented here could provide the key advantage of reducing adverse side effects of anti-TERT treatments, since the TERT inhibition is specific for the cancer cells harboring the SNV target for the ASEE complex." (PMID 37993930, 2023).
cancer (continued). "Overall, our data represent an advance in our understanding of TERT regulation in stem cells and cancer cells." (PMID 37531400, 2023). "Overall, our findings represent an important step forward in understanding the regulation of TERT AS in stem cells and cancer cells." (PMID 37531400, 2023). "In studies using cancer cells, splicing of the TERT reverse transcriptase domain has been focused on because of its importance in telomerase activity." (PMID 37531400, 2023). "Compared to clinically applicable GWs, (Z)-BP in CW can not only reduce nuclear receptor subfamily 4 group A member 1 (Nur77) to increase cancer cell apoptosis, but also inhibit telomerase reverse transcriptase (TERT) to promote cell senescence." (PMID 35646111, 2022). "Mutations of the TERT promoter are the major genomic alterations leading to TERT overactivation in most cancer types." (PMID 36313663, 2022). "Engagement of the TERT promoter by ETS proteins stimulates TERT transcription, providing a mechanistic connection between cancer associated TERT mutations and telomerase reactivation." (PMID 35159075, 2022). "Cancers develop mechanisms to bypass the replicative senescence and become immortal through upregulation of telomerase reverse transcriptase (TERT), which is a subunit of the holoenzyme that elongates telomeres." (PMID 36203452, 2022). "Intriguingly, several clinical trials of a TERT-peptide vaccine have been shown to have activity against several cancers, including nonsmall cell lung cancer, prostate cancer, and multiple myeloma." (PMID 35356211, 2022). "Although the molecular mechanisms of TERT regulation have been described in detail in many cancers, it is not well understood in BC." (PMID 35563554, 2022). "HOXC5 transcription factor is also involved embryonic development; however, the deregulation of HOXC5 has been shown to contribute to activation of the TERT gene in human cancers." (PMID 35629968, 2022). "PinX1, known as a potent TERT inhibitor, also contributes to cellular aging and cancer tumorigenicity." (PMID 35847001, 2022). "To test if the connection between proliferation and mutant TERTp regulation is more universal, we serum starved 13 cell lines representing the seven most common TERTp-mutant cancers and observed decreased TERT expression in 12 of them." (PMID 36130485, 2022). "Taken together, these findings highlight the ability to TERT to oversee multiple metabolic and cellular detoxification functions that substantially influence cancer cell survival, adaptation, and dissemination." (PMID 35159075, 2022). "Herein, we focused on the promoter region of human TERT oncogene, whose product is responsible for the immortality of cancer cells." (PMID 36009419, 2022). "In wild-type cancer cell lines, both epialleles were hypermethylated symmetrically on the TERT distal promoter." (PMID 36011010, 2022). "Research targeting the telomerase reverse transcriptase (TERT) promoter contributes to a better understanding of cancer development and treatment." (PMID 35053139, 2022). "Upregulation of TERT (telomerase reverse transcriptase) gene leads to telomerase activation in cancers." (PMID 36612286, 2022). "They found that Dabrafenib and Trametinib induced strong apoptosis in cancer cells carrying both BRAF V600E and TERT promoter mutations but had a little proapoptotic effect in cells that only carry BRAF V600E." (PMID 35903534, 2022). "PARP1 is therefore proposed to promote KLF4 binding to its promoter to maintain TERT expression in stem and cancer cells, thereby contributing to pluripotency and cell proliferation." (PMID 35348914, 2022). "Introduced modifications blocked the binding of E26 transcription factor family members to the TERT promoter, reduced TERT transcription as well as TERT protein expression, and induced cancer cell senescence and proliferative arrest." (PMID 36361634, 2022).
cancer (continued). "TERT, the telomerase reverse transcriptase gene, is found to be reactivated in many cancer cells and enables cancer cells to evade senescence resulting from telomere shortening." (PMID 36564761, 2022). "Epigenetic targeting of mutant TERT transcription remains an attractive yet ambitious goal due to the high prevalence of TPMs in advanced tumors and the cancer-specific nature of this approach." (PMID 35053525, 2022). "These TERT promoter mutations increased the transcriptional activity of the TERT promoter by 2–4 times, resulting in elevated TERT gene expression and telomerase levels in cancers." (PMID 35903534, 2022). "While the identity of TERT transcriptional regulators can be highly cancer-specific, there exists a set of shared TFs that serve to influence TERT expression across numerous cancer types." (PMID 35159075, 2022). "The generation of clones that are DTX2 KO in telomerase-positive cancer cells significantly reduced TERT mRNA levels as well as telomerase activity, resulting in progressive telomere shortening, cell growth arrest and increased apoptosis." (PMID 36497228, 2022). "By targeting a G4 in the TERT promoter with a small molecule, the expression of telomerase was down-regulated in cancer cells." (PMID 35573091, 2022). "Nevertheless, numerous clinical research has positively evaluated telomerase activation, especially TERT-related changes, as prognostic factors for cancer patients." (PMID 35327529, 2022). "TERT promoter mutations generate novel transcription factor binding sites, contributing to increased TERT expression in cancer cells." (PMID 36741696, 2022). "Mutations in PTPRD, CREBBP, BRAF, NOTCH3, TERT, and SETD2, which are involved in various aspects of immune regulation, were reported as potential biomarkers in cancer patients after immunotherapy with improved survival." (PMID 36092890, 2022). "TERT promoter mutations associated with cancer formation have created new binding sites for ETS (E26) family transcription factors and increased TERT expression." (PMID 35903534, 2022). "Given that serum starvation reduced TERT expression in the most common TERTp-mutant cancers, it is possible that other drivers of proliferation regulate TERT in different genetic backgrounds." (PMID 36130485, 2022). "To conclude, in our study, it was identified that 12 variants in the TERT-CLPTM1L genes were rated as revealing strong evidence for a significant correlation with eight cancers and one non-cancer disease risk." (PMID 35847915, 2022). "Further studies are needed to examine the transcriptional effects of methylation in wild-type cancers by specifically targeting different regions of the TERT promoter." (PMID 36011010, 2022). "Severe telomere shortening and abnormal expression of TERT and shelterin-complex genes were previously correlated with cancer prognosis." (PMID 36612286, 2022). "Cancer cell lines with a heterozygous TERT genetic alteration only express the genetically altered allele." (PMID 36011010, 2022). "We ran a targeted next generation sequencing (NGS) custom pediatric cancer gene panel featuring 2247 coding exons of 124 genes as well as the TERT promoter." (PMID 35451474, 2022). "In seven cancer types, we identify duplications of wildtype sequence within the core promoter region of TERT that have strikingly similar features including an ETS motif, the duplication length and insertion site." (PMID 36114166, 2022). "It is known that upregulation of TERT increases telomerase activity, the basic survival ability of cancer cells, which allows for unlimited expansion of telomeres, and immortalization of cells." (PMID 34558656, 2022). "The activity of the catalytic subunit of telomerase (TERT) is universally enhanced in virus-related cancers." (PMID 36358677, 2022). "In pan-cancer mutation analysis according to cBioPortal, CDKN2A showed the highest mutation types with deep deletions, followed by TERT, TRIM, and ZBP with a frequency of 11% amplifications." (PMID 35911707, 2022).